SOD1 (superoxide dismutase 1)
Diseases named in the same sentence as SOD1 in open-access papers (continued):
Sharing a sentence is not in itself a finding about the gene and the disease.
infertile (54 papers, 2007 to 2025). "Overall, oocyte specific deletion of Sod1 increased the rate of follicle loss and predisposed mice to infertility." (PMID 39297300, 2025). "Superoxide neutralization by SOD1 is a crucial mechanism in counteracting oxidative damage, as SOD1 knockout Drosophila exhibits reduced lifespan, infertility, and hypersensitivity to oxidative stress." (PMID 37582934, 2023). "Only infertile women with moderate/severe endometriosis had increased SOD1 expression incumuluscells, compared to women with minimal/mild endometriosis and controls, with positive interaction between increased expression and occurrence of clinical pregnancy." (PMID 32759095, 2021). "There is a greater expression of the SOD1 gene in infertile patients with moderate/severe endometriosis, when compared with healthy infertile patients or those with mild endometriosis." (PMID 32759095, 2021). "In the context of comparisons between fertile and infertile men, the present study represents the only report investigating the concentrations of the enzymes SOD, GPX, and NOS in seminal plasma, specifically focusing on their individual isoforms (SOD1, GPX1, and NOS1)." (PMID 41462670, 2025). "Genetic variation and functional polymorphism in SOD1 and SOD2 may be associated with infertility and low IVF outcome." (PMID 34439451, 2021). "In infertile men, only weak positive correlations were observed, specifically between PGE2 and 6-keto-PGF1α, and between NOS1 and SOD1." (PMID 41462670, 2025). "In the infertile group, PGE2/6-keto-PGF1α negatively correlated with progressive motility, PGE2 positively with 6-keto-PGF1α, and NOS1 positively with SOD1." (PMID 41462670, 2025). "Likewise, in the infertility and asthenozoospermia disease network, PRKACA and SOD1 emerged as shared hub proteins." (PMID 41462610, 2025). "It is possible that SOD1 can compensate for the loss of SOD3 in mouse follicles, as mice lacking SOD1 or both SOD1 and SOD3 are subfertile or infertile, respectively (38, –40)." (PMID 29987037, 2018). "A study in infertile patients with stage III/IV endometriosis who achieved clinical pregnancy after IVF showed higher SOD1 expression compared to a milder case, suggesting SOD1 may protect the oocyte from oxidative damage." (PMID 35721714, 2022). "The evaluation of enzymatic antioxidants gene expression in CC of infertile womenwith and without endometriosis evidenced increased superoxide dismutase 1(SOD1) expression in the moderate/severe endometriosisgroup compared to women with minimal/mild endometriosis and controls." (PMID 31091056, 2019).
schizophrenia (53 papers, 2008 to 2026). A major psychotic disorder characterized by abnormalities in the perception or expression of reality. "Odds ratios (ORs) and 95 % confidence intervals (CIs) were calculated to determine the association between the SOD1 genotypes and the risk of schizophrenia." (PMID 31217783, 2019). "Taken together, we hypothesized that the SOD1 Ins/Del genetic variation might be associated with the schizophrenia risk." (PMID 31217783, 2019). "In post‐mortem clinical studies, increases in SOD1 and SOD2 levels were found in frontal cortex of patients with schizophrenia and in prefrontal cortex of depressive subjects." (PMID 32281745, 2020). "In our study, many RB (CAT, GR, SOD-1, FRAP, AGEs, DITYR, NFK, TYR) were not related to schizophrenia." (PMID 34575267, 2021).
periodontitis (50 papers, 2014 to 2026). An acute or chronic inflammatory process that affects the tissues that surround and support the teeth. "Alterations in the SOD1 expression have been linked to periodontitis, however, data are still inconclusive, since some studies report increase in the SOD expression/activity while others indicate decline." (PMID 32267380, 2020). "For SOD1, the unmethylated profile was the most frequent in both groups (85% of the control group and 79% of the periodontitis group)." (PMID 32267380, 2020). "Considering that gene expression may be controlled by DNA methylation, it is important to consider methylation studies on SOD1 and periodontitis." (PMID 32267380, 2020). "This study aims to investigate the association of polymorphisms C677T in MTHFR (rs1801133) and −149C→T in DNMT3B (rs2424913), as well as the methylation profiles of MTHFR, miR-9-1, miR-9-3, SOD1, and CAT with periodontitis." (PMID 32267380, 2020). "Therefore, the main objective of this study was to investigate the association between the MTHFR rs1801133 and the DNMT3B rs2424913 polymorphisms, and methylation profiles from MTHFR, miR-9-1, miR-9-3, superoxide dismutase (SOD1), and catalase (CAT) genes with periodontitis." (PMID 32267380, 2020).
frontotemporal dementia (49 papers, 2011 to 2025). Frontotemporal dementia (FTD) comprises a group of neurodegenerative disorders, characterized by progressive changes in behavior, executive dysfunction and language impairment, as a result of degeneration of the medial prefrontal and frontoinsular cortices. "Patients with a mutation in SOD1 were reported as having frontotemporal dementia (FTD) and decline of cognitive function was rare." (PMID 27716404, 2016). "Only one patient with a mutation in SOD1 showing frontotemporal lobar degeneration (FTLD) underwent a detailed clinicopathological analysis." (PMID 27716404, 2016). "As examples, C9ORF72 carriers have a higher incidence of fronto-temporal dementia, the specific A4V SOD1 mutation carries a poor prognosis, and certain UNC13A single nucleotide variants have been associated with shorter survival and others with longer survival." (PMID 31001186, 2019). "Aberrant α-Syn, SOD1, and PrP cause neurodegeneration and cognitive deterioration in humans linked to PD, MSA, ALS-frontotemporal dementia, and CJD and are recognized as targets for therapy." (PMID 40277911, 2025). "They used the mouse models of ALS, G93A SOD1 and frontotemporal dementia (FTD), P30L Tau and isolated both motor neurons and glia for microarray analysis." (PMID 24381542, 2013). "In neuropsychological screening, C9orf72 patients displayed abnormal results in memory, verbal fluency and executive functions, showing generally worse performances compared to SOD1 and sporadic patients and a higher share with suspected frontotemporal dementia." (PMID 37006326, 2023). "Changes in SOD1 associated function leading to a concomitant deficit in proteostasis may therefore be a unique feature of ALS pathology and its close relative frontotemporal dementia." (PMID 35576218, 2022). "We focused on the TDP-43G298S transgenic mouse model because, in contrast to the mutant SOD1 model, it may more faithfully mimic the pathogenic cascades and the neuropathological hallmarks observed in human patients affected by sporadic ALS, frontotemporal dementia (FTD), and related conditions." (PMID 31485326, 2019). "Moreover, mutation in the copper-zinc superoxide dismutase 1 (SOD1) gene has been associated with ALS, while the alteration of MAPT genes or progranulin is linked to frontotemporal dementia (FTD)." (PMID 37242804, 2023). "SOD1, TDP-43, frontotemporal dementia, and C9orf72 appeared to be pivotal in the molecular mechanisms of ALS." (PMID 36033620, 2022). "Since the first identification of superoxide dismutase 1 (SOD1) as an ALS causative gene in 1993, significant research efforts and advanced genetic approaches have identified mutations in more than 30 genes that cause ALS and frontotemporal dementia (FTD)." (PMID 33807542, 2021). "FUS-positive inclusions have been detected in non-SOD1 ALS patient specimens, frontotemporal lobar degeneration, and neuronal intermediate filament inclusion disease." (PMID 23620769, 2013). "Association of SOD1 with module-1 proteins (PSMD2, ADRM1, RAD23A) were involved in ALS15-type with or without Frontotemporal dementia." (PMID 34918006, 2022). "ALS is associated with several genes, for example, C9ORF72, TARDBP, SOD1 and FUS, with some genes also contributing to the presence of frontotemporal dementia (FTD)." (PMID 33094283, 2020).
diabetic nephropathy (45 papers, 2010 to 2025). "We previously reported that renal SOD1 deficiency accelerates the progression of diabetic nephropathy (DN) via increasing renal oxidative stress." (PMID 34071003, 2021). "In kidney tissue, SOD-1 upregulation attenuates uric acid–kidney fibrosis, while its downregulation accelerates the progression of diabetic nephropathy and decreases lifespan and accelerated aging process, especially in the renal tissue." (PMID 37760081, 2023). "Either inadequate SOD1 or SOD3 expression is found to be involved in microvascular and macrovascular complications and is associated with the severity of proteinuria in diabetic nephropathy." (PMID 33138205, 2020). "SOD, a major defender against superoxide, in the kidneys during the development of murine diabetic nephropathy and downregulation of renal SOD (SOD 1 and SOD 3) may play a key role in the pathogenesis of diabetic nephropathy." (PMID 26317014, 2013). "Since Nox4 is the major source of ROS in the kidneys during the early stages of diabetic nephropathy and in order to confirm the effect of TGFβ1 on ROS production, the levels of SOD1, which constitutes the first line of defence against ROS were determined following TGFβ1 treatment." (PMID 23991195, 2013). "The same group reported using SOD1- and SOD3-knockout diabetic mice to confirm the distinct role of SOD isoforms in diabetic nephropathy." (PMID 33477607, 2021). "They suggested that SOD1 deficiency, but not SOD3 deficiency, increases renal O2•− and causes overt renal injury in C57BL/6-Akita diabetic mice and that SOD1 plays a more prominent role than SOD3 in the pathogenesis of diabetic nephropathy." (PMID 33477607, 2021).
injury (45 papers, 2011 to 2026). Damage inflicted on the body as the direct or indirect result of an external force, with or without disruption of structural continuity. "ROS removal is regulated by many antioxidant enzymes, including SOD1, SOD2, GPX, and catalase, and overexpression of SOD2 protects against alcohol-induced liver injury." (PMID 24069053, 2013). "Similarly, we also noticed that PDTC enhanced SOD1 expression, suggesting that PDTC improve antioxidant balance in LPS-induced acute lung injury in mice." (PMID 28521300, 2017). "However, CA3 as well as SOD1 and CaM were present in human urine samples after APAP intoxication, and are, therefore, proposed as potential urinary biomarkers for APAP-induced liver injury." (PMID 23166697, 2012).
motor neuron degeneration (44 papers, 2008 to 2025). "These mice are characterized by aggressive weight loss following progressive spinal motor neuron degeneration and exhibit large SOD1-immunopositive inclusions within surviving spinal motor neurons." (PMID 40042537, 2025). "ALS has been attributed to gain-of-function mutations in the gene-encoding Cu/Zn superoxide dismutase 1 (SOD1) in which SOD1 point mutation in an ALS mouse model causes motor neuron degeneration." (PMID 40558500, 2025). "Mutations to the SOD1 gene, together with atypical post-translational modification of SOD1 protein, promote misfolding, dysfunction and deposition of the protein, which are collectively strongly implicated in motor neuron degeneration in this disorder." (PMID 36008843, 2022). "Several genes mutated in ALS patients and implicated in motor neuron degeneration have been studied in zebrafish, including superoxide dismutase (SOD1), alsin (ALS2), the elongated protein 3 (ELP3), FUS, and TDP-43." (PMID 33499374, 2021). "Another study reported that muscle-restricted expression of the human mutant SOD1 gene causes motor neuron degeneration in old transgenic mice." (PMID 34936028, 2021). "Recently, it has been suggested that there is a potential link between TDP-43 and SOD-1 mutations, previously thought to be pathologically distinct pathways of motor neuron degeneration involved sALS and in fALS." (PMID 29982983, 2019). "Interestingly, data obtained in ALS mouse models, based on the pathological G37R or G93A SOD1 mutations, highlighted copper incorporation into the SOD1 active site, rather than amino-acid mutations, per se, as a major determinant for motor neuron degeneration." (PMID 37108835, 2023). "Given that both SOD1 and TDP-43 are associated with motor neuron degeneration in patients with ALS, we aimed to determine if mutant SOD1 expression directly causes biochemical alterations of TDP-43 related to motor neuron degeneration in a NSC34 cell line transiently transfected with mutant SOD1." (PMID 29982983, 2019). "Evans blue extravasation from capillaries into spinal cord parenchyma was found in early symptomatic SOD1 transgenic (G93A) mice but it was uncertain whether BBB/BSCB disruption was cause or effect of motor neuron degeneration." (PMID 30804878, 2019). "Our particular questions are how more than 130 different SOD1 mutations all result in motor neuron degeneration, and how a low level of mutant SOD1 expression, like SOD1L126delTT leads to FALS in a similar manner to high level expression that is seen with point mutations." (PMID 18946506, 2008). "Although understanding of the physicochemical properties of wild-type human SOD1 and its various mutations has continually improved since its identification as an ALS-causative risk factor, how SOD1 mutations actually cause motor neuron degeneration remains unclear." (PMID 31040321, 2019). "Mutations in SOD1 are associated with ALS, a disease causing motor neuron atrophy and subsequent mortality." (PMID 39458929, 2024). "Some previous reports showed that the administration of anti-human SOD1 antibody improved disease symptoms, prolonged their lifespan, and reduced the aggregation of misfolded SOD1 protein and motor neuron degeneration in mSOD1 mice." (PMID 37992159, 2023). "Approximately 20% of familial cases and 3% of sporadic cases of ALS are associated with mutations in the gene encoding superoxide dismutase-1 (SOD1) 4, but the molecular mechanisms linking this mutation to motor neuron degeneration has yet to be unsolved." (PMID 34158851, 2021). "The identification by Garbuzova-Davis and her colleagues that BSCB dysfunction occurred in both ALS patients and fALS SOD1 mice, prior to motor neuron degeneration, has been confirmed by other groups." (PMID 30804878, 2019). "Mutations in the antioxidant enzyme, superoxide dismutase 1 (SOD1), are associated with motor neuron degeneration." (PMID 29469808, 2018).
motor neuron degeneration (continued). "The first study reported that immediate treatment with edaravone (15 mg/kg/day) after disease onset delayed progression of motor symptoms and motor neuron degeneration in mutant SOD1 (G93A)-transgenic mice." (PMID 26469273, 2015). "Two previous studies showed that edaravone attenuated motor symptoms or motor neuron degeneration in mutant superoxide dismutase 1-transgenic mice or rats, animal models of familial ALS." (PMID 26469273, 2015). "In the present study, we found that mRNA oxidation is a common feature in ALS patients and mutant SOD1 transgenic mice and also an early event preceding motor neuron degeneration." (PMID 18682740, 2008). "Intraperitoneal injection of bosutinib (5 mg/kg) into transgenic SOD1-G93A mice daily starting at 8 weeks of age for 5 weeks, reduced misfolded SOD1 and motor neuron degeneration in spinal cords, as well as delaying disease onset by 10.8 days and extending survival by 7.8 days." (PMID 33328890, 2020). "Despite identification of the first gene linked to familial ALS (FALS), Superoxide Dismutase 1 (SOD1) over twenty years ago, and the discovery of many more ALS genes since, the causes of motor neuron degeneration remain unknown." (PMID 27121871, 2016). "ALS is a multifactorial disease caused by motor neuron degeneration that can be divided into a sporadic (90% of the cases) and a familial form (fALS) whose 20% of mutations (2% of total ALS cases) map throughout the SOD1 gene (coding the Cu, Zn superoxide dismutase)." (PMID 26491229, 2015). "Mitochondrial dysfunction has been identified as one of the earliest defects in motor neurons of transgenic SOD1 mice and it has been suggested that mitochondrial dysfunction may play a pivotal role in motor neuron degeneration in ALS." (PMID 25468678, 2015). "Indeed, dynein mutant mice were initially thought to develop motor neuron degeneration, and it appeared difficult to understand how mutating dynein, and thus precipitating late onset motor neuron degeneration, might protect against early onset SOD1(G93A)-mediated neurodegeneration." (PMID 21521523, 2011). "Our findings indicate that SOD1 protein may be removed directly through the increased activity of PSA/NPEPPS, and implicate this enzyme as an important modulator of SOD1-induced motor neuron degeneration in ALS." (PMID 21548977, 2011). "While PFN1 and SOD1 do not share functional similarities, their mutated forms display comparable patterns in neuropathology, particularly concerning the ongoing progression of motor neuron degeneration (Lim, Kang & Song, 2017)." (PMID 38912047, 2024). "We further hypothesize that some of the genetic modifiers located in the Chr 17 region where the SOD1 and dynactin-1 QTLs overlap, will be shared by these two MND models despite the fact that motor neuron degeneration is caused by mutations in different proteins." (PMID 36107978, 2022). "In the Superoxide dismutase 1 (SOD1) mouse model of ALS, elevation in levels of Hsp70 by another agent, arimoclomol, protected motor-neurons in both acute injury-induced motor-neuron degeneration as well as progressive motor-neuron degeneration models." (PMID 20525284, 2010). "Motor neuron degeneration involving TDP-43, FUS, and SOD1 remains a central theme in ALS research." (PMID 39659885, 2024). "Previous studies assessing the spinal cord have shown that subtle damage in ALS patients following needle injections and even severe damage resulting from stab-wound trauma in the SOD1 rat did not accelerate motor neuron degeneration." (PMID 26464984, 2015). "To investigate the potential linkage between low NRIP expression in SOD1 G93A mice and progressive motor neuron degeneration, we aimed to assess whether forced NRIP expression in SOD1 G93A mice could have therapeutic effects through adeno-associated virus (AAV) gene therapy." (PMID 39044305, 2024). "Importantly however, several reports show that aged Sod1−/− mice do not develop motor neuron degeneration at any age." (PMID 25468678, 2015).